MYOF (myoferlin)
Diseases named in the same sentence as MYOF in open-access papers (continued):
Sharing a sentence is not in itself a finding about the gene and the disease.
breast carcinoma (continued). "Our findings suggest that MYOF can be explored as a molecular target in breast cancer metastasis and that targeting MYOF by WJ460 may be a promising therapeutic strategy in MYOF-driven cancers." (PMID 30213946, 2018). "In our results, melanoma cells migration distance observed in Would healing assay was not robustly decreased after MYOF depletion, which correlated to that observed in breast cancer cells." (PMID 29164766, 2018). "In breast cancer, in vivo tumor xenografts lacking myoferlin have been described as smaller, less invasive and less vascularized than their control counterparts." (PMID 27845903, 2016). "In contrast, when MYOF was depleted with RNAi, implanted breast cancer cells produced smaller, smooth-bordered tumors that did not appear to invade into the local adventia." (PMID 24586247, 2014). "Unlike that in endothelial cells or breast cancer cells, knockdown of MYOF in renal cell carcinoma cells may affect one of the VEGFR2-mediated downstream signaling pathways not related to tumor cell migration." (PMID 31477752, 2019). "Notably, tumors of patients with metastatic breast cancer have higher MYOF levels (52.5%) than adjacent non-cancerous tissues (12.5%) and tumors from patients with in situ breast carcinoma (25%)." (PMID 30213946, 2018). "In this study, we used an Ibidi cell culture insert and live-cell tracking routines to evaluate the migratory properties of MDA-MB-231 breast cancer cells with shRNA-mediated knockdown of MYOF and cells treated with a lentiviral non-human, non-targeting control vector." (PMID 24586247, 2014).
pancreatic cancer (24 papers, 2016 to 2025). "We also proved that MYOF expression level was also associated with the stage of pancreatic cancer, with higher expression at advanced stages." (PMID 34957301, 2021). "Immune response is implicated in the tumorigenesis of pancreatic cancer and dysferlinopathy mediated by dysferlin, a similar protein of MYOF." (PMID 34957301, 2021). "The results display that MYOF is abnormally highly expressed in pancreatic cancer and the upregulation is associated with poor prognosis." (PMID 34957301, 2021). "In order to unravel the mechanism underlying this observation, we explored the myoferlin localization in pancreatic cancer cells and showed a colocalization with the mitochondrial dynamic machinery element: mitofusin." (PMID 32575867, 2020). "The results revealed that the MYOF gene seldom mutated in pancreatic cancer (1%)." (PMID 34957301, 2021). "MYOF has been identified to be associated with pancreatic cancer diagnosis and treatment." (PMID 34957301, 2021). "Besides, datasets from GEPIA and LOGpc reveal that high MYOF expressions in pancreatic cancer patients are significantly associated with unfavorable prognosis." (PMID 34957301, 2021). "High expression of MYOF is associated with high density of blood vessels in pancreas cancer." (PMID 31828126, 2019). "While the specificity of myoferlin targeting has already been assessed previously in pancreatic cancer cells, we validated that WJ460 indeed impaired ECM production dose-dependently in myCAFs, in accordance with MYOFKD (Fig. EV7B–F)." (PMID 41062852, 2025). "In this work, we described a pleiotropic expression of the vesicle trafficking protein myoferlin across CAF subtypes in the pancreatic tumor microenvironment and identified stromal myoferlin as driver for tumor aggressiveness." (PMID 41062852, 2025). "Alternatively, SLC16A1 and MYOF showed a trend toward increased expression in pancreatic cancer tissues." (PMID 39897130, 2025). "Myoferlin promotes pancreatic tumor fibrosis by enabling COPII-dependent trafficking of TGFß receptor 1 in the tumor stroma." (PMID 41062852, 2025). "We further elucidated that stromal myoferlin abundance, in contrast to cancer cell myoferlin abundance, impaired patient survival in pancreatic cancer." (PMID 41062852, 2025). "Targeting the oncogene Myoferlin in pancreatic cancer cells triggers mitophagy and promotes ferroptosis, indicating the priming role of mitophagy in tumor cell ferroptosis." (PMID 38395990, 2024). "This study identifies and validates a novel five-gene transcriptomic signature (LAMC2, TSPAN1, MYO1E, MYOF, and SULF1) as both diagnostic biomarkers and potential drug targets for pancreatic cancer." (PMID 39850570, 2024). "In this analysis, BxPC3 pancreatic cancer cells served as a positive control, as these cells display high MYOF expression." (PMID 36827461, 2023). "MYOF has been found to be highly expressed in lipogenic pancreatic cancer cells, and to be involved in maintaining high oxidative phosphorylation (OXPHOS) activity and mitochondrial network structure." (PMID 36147922, 2022). "Myoferlin had been found to maintain mitochondrial structure and oxidative phosphorylation in pancreatic cancer and to interact with mitofusin, indicating that myoferlin modulates mitochondrial dynamics, resulting in mitochondrial fusion." (PMID 36147922, 2022). "Increased MYOF is associated with poor overall survival (OS) and poor disease-free survival (DFS) in pancreatic cancer." (PMID 34957301, 2021). "Here, we systematically analyzed the expression, prognosis, and coexpressed genes of MYOF in pancreatic cancer patients using public data." (PMID 34957301, 2021). "It has been reported that myoferlin (MYOF) is implicated in the regulation of proliferation, invasion, and migration of tumor cells in many cancers including pancreatic cancer." (PMID 34957301, 2021).
pancreatic cancer (continued). "The dysregulated expression level of MYOF and its relationship with clinicopathological features and prognosis have been partly reported in human pancreatic cancer." (PMID 34957301, 2021). "MYOF mRNA expression levels were compared in many kinds of cancers including pancreatic cancer via the Oncomine and Gene Expression Profiling Interactive Analysis (GEPIA) databases." (PMID 34957301, 2021). "Data from the Cancer Cell Line Encyclopedia (CCLE) and European Bioinformatics Institute (EMBL-EML) database also revealed that MYOF mRNA is highly expressed in most cancer cells, particularly in pancreatic cancer cell lines." (PMID 34957301, 2021). "The results have shown that MYOF mRNA expression levels were upregulated in most types of cancers, especially in pancreatic cancer, compared with healthy people's tissues." (PMID 34957301, 2021). "To further explore the possible regulators of MYOF in pancreatic cancer, we analyzed the kinase, miRNA, and transcription factor enrichment of MYOF coexpressed genes using the LinkedOmics database." (PMID 34957301, 2021). "In summary, this study provides many evidences at different levels for the key role of MYOF in pancreatic cancer and its potential as a prognostic biomarker in it." (PMID 34957301, 2021). "Then, the top one hundred genes similarly expressed with MYOF in pancreatic cancer were identified using GEPIA2." (PMID 34957301, 2021). "Our study shows that MYOF is more highly expressed in both pancreatic cancer patients and pancreatic cancer cell lines than in healthy tissues and cells." (PMID 34957301, 2021). "MYOF has been shown to be overexpressed in pancreatic tumors based on whole-genome gene expression profile analysis and proteomics results." (PMID 34957301, 2021). "As it stands for now, our findings clearly demonstrate a physical interaction between myoferlin and mitofusins in pancreas cancer cells." (PMID 32575867, 2020). "The discovery of a mitofusin–myoferlin interaction in PDAC cell lines opens up new research avenues aiming at modulating mitofusin function in pancreas cancer." (PMID 32575867, 2020). "In order to illustrate the functional role of myoferlin in mitochondria of pancreas cancer cells, we investigated mitochondrial network, mitochondrial ultrastructure and oxygen consumption rate (OCR) in myoferlin-depleted Panc-1 cells." (PMID 32575867, 2020). "These discoveries will open up new research avenues aiming at modulating mitofusin function or targeting myoferlin to fight pancreas cancer." (PMID 32575867, 2020). "MYOF also abounds in lipogenic pancreatic cancer cell lines and is important for mitochondrial fitness as well as energy production through OXPHOS." (PMID 31828126, 2019). "We found out that myoferlin is more abundant in lipogenic pancreatic cancer cell lines and is required to maintain a branched mitochondrial structure and a high oxidative phosphorylation activity." (PMID 29720728, 2018). "A study of pancreatic cancer determined MYOF to be critical for the exocytosis of VEGF, and staining of VEGF and vesicle markers identified an aggregation of vesicles at the cell membrane following MYOF silencing." (PMID 29721195, 2018). "Taking advantage of The Cancer Genome Atlas (TCGA) data for a pancreatic cancer cohort (n = 179), we performed an overall survival analysis in accordance with the expression level of the myoferlin gene." (PMID 29720728, 2018). "We also showed that myoferlin is more abundant in lipogenic pancreatic cancer cell lines than in glycolytic one, and is required to maintain a high OXPHOS activity." (PMID 29720728, 2018). "Using immunoblotting and electron microscopy, we confirmed that myoferlin is indeed present in exosomes derived from breast and pancreas cancer cells." (PMID 27845903, 2016). "To validate these in silico data, we purified exosomes from the supernatant of breast and pancreatic cancer cell lines, and evaluated myoferlin expression using Western blot." (PMID 27845903, 2016).
pancreatic cancer (continued). "Our data expand these findings by showing that myoferlin is a general component of cancer cell derived exosomes from different breast and pancreatic cancer cell lines." (PMID 27845903, 2016). "We further confirm that myoferlin is present in exosomes derived from all major breast and pancreatic cancer cell lines from different genetic backgrounds." (PMID 27845903, 2016). "Accordingly, ORA on cancer cell-specific DEGs showed a downregulation of mitochondria-related genes, in agreement with the described mitochondrial role of myoferlin in pancreatic cancer cells (Fig. EV6), suggesting that a COPII-related function of myoferlin is only minor in cancer cells." (PMID 41062852, 2025). "This research highlights myoferlin as a potential therapeutic target that may offer a novel strategy for the treatment of pancreatic cancer." (PMID 40733146, 2025). "While several studies describe myoferlin functions in pancreatic cancer cells, the stromal role of myoferlin remains unknown." (PMID 41062852, 2025). "Because MYOF had been shown to be involved in sustaining enhanced lysosome function in pancreatic cancer by defending against membrane stressors, previous studies focused on the role of MYOF in the regulation of intracellular signaling and mitochondrial metabolism in cancer cells." (PMID 36147922, 2022). "In pancreatic cancer cells, MYOF protein was found to localize at lysosome membranes." (PMID 36147922, 2022). "Hence, our results indicate that increased expression of MYOF occurs in many cases of pancreatic cancer and deserves further clinical validation as a candidate biomarker for diagnosis and prognosis." (PMID 34957301, 2021). "We found that most pancreatic cancer cells expressed MYOF highly." (PMID 34957301, 2021). "Hence, MYOF coexpresses with many cancer-related genes in pancreatic cancer, which also support its prognostic value." (PMID 34957301, 2021). "Notably, MYOF mRNA expression level was significantly upregulated in 6 datasets of pancreatic cancer patients." (PMID 34957301, 2021). "The results indicated that MYOF was overexpressed in most cell lines of pancreatic cancer." (PMID 34957301, 2021). "Previous studies have shown that MYOF might be a candidate biomarker for the diagnosis and prognosis of pancreatic cancer." (PMID 34957301, 2021). "MYOF protein levels in pancreatic cancer tissues were significantly overexpressed." (PMID 34957301, 2021). "MYOF is implicated in the regulation of vascular endothelial growth factor A (VEGFA) secretion and has an impact on tumor-associated angiogenesis in human pancreatic cancer." (PMID 34957301, 2021). "Then, we performed prognosis analysis for MYOF in pancreatic cancer using the GEPIA database." (PMID 34957301, 2021). "Furthermore, compounds targeting MYOF have been shown to inhibit pancreatic cancer metastasis by reversing the epithelial mesenchymal transition, suppressing the secretion of matrix metalloproteinase and blocking the receptor tyrosine kinases." (PMID 34957301, 2021). "Hence, we used the cBioPortal tool to analyze the types and frequency of MYOF alterations in pancreatic cancer." (PMID 34957301, 2021). "Interestingly, recent studies identified new small compounds interacting with the myoferlin C2D domain and demonstrating promising anti-tumoral/metastasis properties in breast and pancreas cancer." (PMID 31443490, 2019). "Therefore, the expression of MYOF in pancreatic cancer increased at both mRNA and protein levels." (PMID 34957301, 2021). "Therefore, we speculated that the role of MYOF in pancreatic cancer might be also related to immunity and inflammation." (PMID 34957301, 2021). "Moreover, in pancreas cancer cell lines, it appeared that myoferlin interacted with mitofusin." (PMID 32575867, 2020). "Moreover, lead compound 6y, one of the 1,5‐diaryl‐1,2,4‐triazole derivatives, targets at myoferlin and prevents pancreatic cancer metastasis, which suggests 6y may also be a promising therapeutic strategy." (PMID 31475450, 2019).
pancreatic cancer (continued). "Moreover, we have recently shown that myoferlin silencing led to a reduced pancreatic tumor growth." (PMID 29720728, 2018). "Researchers have found that targeting myoferlin with a compound WJ460 can induce mitophagy and activate ferroptosis in pancreatic cancer cells." (PMID 40733146, 2025). "We noticed that genes correlated to ITPR3 expression in pancreatic cancer are also correlated to MYOF expression (R = 0.82), while it was not the case in healthy pancreas (R=-0.097)." (PMID 38368370, 2024). "Interestingly, myoferlin is also required for angiogenic cascades by maintaining VEGFR2 and TEK expression in endothelial cells, and VEGFA secretion in pancreatic cancer cells." (PMID 35205843, 2022). "Interestingly, neither IGSF8 nor MYOF have been previously implicated in HGSOC or fallopian tube biology but MYOF in EVs from breast and pancreatic cancer cell lines has been shown to contribute to cancer progression via metastasis." (PMID 37205573, 2023). "In healthy condition, MYOF and ITPR3 expressions were not correlated (R = 0.058, p-value: 0.0017), while in pancreatic cancer their expression appeared strongly and significantly correlated (R = 0.612, p-value: 1.09e-5)." (PMID 38368370, 2024).
muscular dystrophy (12 papers, 2012 to 2022). Muscular dystrophy (MD) refers to a group of more than 30 genetic diseases characterized by progressive weakness and degeneration of the skeletal muscles that control movement. "MyoF-deficient mice have been reported to display marked muscular dystrophy due to the unsuccessful fusion of myoblasts." (PMID 31623157, 2019). "Although MyoF has been proven to be the pathogenic gene of muscular dystrophy, its antagonism against autophagy by stabilizing Dvl-2 has not yet been determined." (PMID 31623157, 2019). "MYOF was first identified as a regulator for muscular dystrophy and subsequent studies implicated it in vesicle-related processes, including endocytosis and vesicle transport." (PMID 30213946, 2018). "A mutation in MYOF (myoferlin) was linked to a muscular dystrophy accompanied by cardiomyopathy." (PMID 32106631, 2020). "The roles of dysferlin and myoferlin in membrane fusion events have primarily focused on skeletal muscles, as mutations particularly in the dysferlin gene are associated with the development of muscular dystrophy, a muscle wasting disease." (PMID 22808170, 2012). "Studies in muscular dystrophy mice showed promoter-recapitulated normal MyoF expression was downregulated in healthy myofibers and was upregulated in response to myofiber damage, indicating that MyoF modulates muscle injury in both myoblasts and myofibers." (PMID 31623157, 2019). "In this study, we found that MyoF is highly expressed in mdx mice and participates in the growth of C2C12 cells, which is in accordance with the report of the unique function of MyoF in muscle regeneration and degeneration in muscular dystrophies." (PMID 31623157, 2019). "Myoferlin has been suggested as a candidate gene and potential modifier for muscular dystrophy, and is required for insulin-like growth factor response and muscle growth." (PMID 28255110, 2017). "Although MYOF mutations have not been described in human muscular dystrophy, we show functional consequences for mature mouse muscle lacking myoferlin." (PMID 34354129, 2021). "However, myoferlin was proposed as a modifier protein for muscular dystrophy phenotype and studies of myoferlin-null mice demonstrated impaired myoblast fusion and myofiber formation during muscle development and regeneration." (PMID 31443490, 2019). "However, unlike dysferlin, no clinical forms of muscular dystrophy due to mutations in myoferlin have been reported." (PMID 34354129, 2021). "In conclusion, our data demonstrate that myoferlin and a minidysferlin can compensate for dysferlin-deficiency in an in vitro assay of sarcolemmal repair but not for the defects in muscle in vivo that lead to muscular dystrophy associated with the absence of dysferlin." (PMID 22666441, 2012). "In previous, a mouse model of muscular dystrophy was established to investigate the function of NFAT in muscle injury, regeneration and repair, and it revealed that the myoferlin, a member of the ferlin family, was regulated bye NFAT in the muscle regeneration." (PMID 35883195, 2022).
clear cell renal cell carcinoma (9 papers, 2017 to 2025). "High expression of Myoferlin is associated with poor patient outcome in oropharyngeal squamous cell carcinoma, and poor prognosis in pancreatic ductal adenocarcinoma, clear cell renal cell carcinoma, and colon cancer." (PMID 35330493, 2022). "Song et al47 uncovered that high myoferlin levels correlate with unfavourable prognosis in clear cell renal cell carcinoma (ccRCC) patients." (PMID 31475450, 2019). "Here, we evaluated myoferlin expression in patients with clear cell renal cell carcinoma (ccRCC) and investigated the prognostic significance of myoferlin expression in these patients." (PMID 29179496, 2017). "MYOF is a prognostic marker in clear cell renal cell carcinoma." (PMID 35320116, 2022). "In studies on clear cell renal cell carcinoma (CCRCC), immunohistochemical data showed a high correlation between MYOF overexpression and low VEGFR2 expression." (PMID 39941891, 2025).
pancreatic adenocarcinoma (9 papers, 2018 to 2025). "It was intriguing to find that MYOF is also highly expressed in several other tumor types such as lung adenocarcinoma, pancreatic adenocarcinoma and sarcoma when we analyzed the The Cancer Genome Atlas and cBioPortal database." (PMID 30213946, 2018). "Pancreatic adenocarcinoma (PAAD) cells exploit vesicle trafficking proteins, such as myoferlin (encoded by MYOF), to fuel tumor aggressiveness, yet the presence and function of myoferlin-dependent vesicles in cancer-associated fibroblasts (CAFs) remain unknown." (PMID 41062852, 2025). "In pancreas adenocarcinoma (PAC), MYOF expression is negatively correlated with the degree of histological differentiation and patients with MYOF-overexpressing MYOF have poor total survival rate after surgical treatment." (PMID 31828126, 2019).